NF2 (NF2, moesin-ezrin-radixin like (MERLIN) tumor suppressor)
Diseases named in the same sentence as NF2 in open-access papers (continued):
Sharing a sentence is not in itself a finding about the gene and the disease.
schwannoma (266 papers, 2008 to 2026). A benign, usually encapsulated slow growing tumor composed of Schwann cells. "Integrating RNA sequencing, multiple NF2 schwannoma mouse models and primary human VS cultures, we demonstrate that N-cad is overexpressed in sporadic and NF2-associated VS." (PMID 41756440, 2026). "Café-au-lait macules and neurofibromas are hallmark features of NF1, whereas NF2 is primarily characterized by schwannomas, meningiomas, and ependymomas; NF3 is characterized by multiple schwannomas typically sparing the vestibular nerves." (PMID 41515658, 2026). "We conducted experiments to knock down and overexpress HSP90 in NF2-associated schwannoma cells, subsequently extracting sEVs (designated as NF2-EVs HSP90KD and NF2-EVsHSP90OE) from their supernatants." (PMID 41149489, 2025). "Biallelic loss-of function of the NF2 gene is the initiating tumorigenic event of schwannomas in patients with NF2-related SWN and also in a large proportion of sporadic schwannomas [reviewed by 384]." (PMID 40794298, 2025). "The NF-related cases included both NF1- and NF2-associated tumors, encompassing optic pathway gliomas, low-grade gliomas, neurofibromas, and schwannomas." (PMID 40313757, 2025). "A causal link exists between schwannoma tumorigenesis and merlin tumour suppressor protein, produced by the NF2 gene located on chromosome 22q12.2." (PMID 40255781, 2025). "The size distribution analysis of the sEVs was performed using ZetaView (version 8.04.02), indicating that sEVs derived from NF2-associated schwannoma ranged in size from 50 to 200 nm." (PMID 41149489, 2025). "The NF2-associated schwannoma exhibited a distinct miRNA expression profile compared to that in the sporadic schwannomas and normal nerve tissues." (PMID 40843672, 2025). "Pathology confirmed schwannoma with neurofibromatosis type 2 (NF2) mutation in the tumor but normal NF2 germline." (PMID 39917261, 2025). "Small extracellular vesicles (sEVs) derived from NF2-associated schwannomas (NF2-EVs) express CD9 and CD81, with a size distribution ranging from 50 to 200 nm." (PMID 41149489, 2025). "Hybrid neurofibromas/schwannomas are associated with NF1, NF2, and schwannomatosis, whereas hybrid schwannomas/perineuriomas occur sporadically." (PMID 40255822, 2025). "Subsequent Western blot analysis further validated that HSP90 is markedly upregulated in NF2-associated schwannoma tissues." (PMID 41149489, 2025). "Through a series of gain and loss of function experiments, we uncovered that HSP90 plays a vital role in both the transformation of MDSCs and the proliferation of NF2-associated schwannoma cells." (PMID 41149489, 2025). "We were also able to confirm that some of the major YAP and PI3K/AKT/mTOR pathway target genes, known to be altered in both NF2(−/−) primary SCs and schwannomas, were significantly up-regulated in NF2 deficient SC-like spheroids." (PMID 40746735, 2025). "SEVs were isolated from the supernatant of primary cell cultures derived from NF2-associated schwannoma tissues." (PMID 41149489, 2025). "In this study, t-166 and T-153 were anonymised NF2-associated schwannoma samples labelled with alphanumeric codes." (PMID 40843672, 2025). "In summary, our findings highlight the important role of sEV’s HSP90 in regulating both the immune response and the proliferation of NF2-associated schwannoma cells." (PMID 41149489, 2025). "The co-involvement of SMARCB1 and NF2 in the pathogenesis underlying schwannomas in patients with SMARCB1-related SWN is substantiated by mouse models of schwannoma development (Sect." (PMID 40794298, 2025). "Pathology showed a World Health Organization grade 1 schwannoma and next-generation sequencing identified an NF2 mutation in the tumor." (PMID 39917261, 2025). "Our study revealed that HSP90 is highly expressed in NF2-EVs and plays a pivotal role in enhancing the proliferation of NF2-associated schwannoma cells while also promoting the transformation of MDSCs in NF2-SWN." (PMID 41149489, 2025).
schwannoma (continued). "Histological features more commonly seen in CPS-associated schwannomas include whorl formation and involvement of multiple nerves in NF2 and “peritumoral edema, myxoid changes, intraneural growth, and intratumoral nerve fibers” in schwannomatosis." (PMID 39847050, 2025). "While schwannomas are more commonly associated with NF-2, these can be seldom encountered with NF-1." (PMID 40416267, 2025). "In this study, we found that sEVs secreted by NF2-associated schwannomas (NF2-EVs) facilitate the conversion of CD14+ monocytes into an MDSC-like phenotype, showcasing MDSC-like inhibitory functions." (PMID 41149489, 2025). "Schwannomas often appear as asymptomatic, incidental findings on chest imaging, and also have been associated with mutations in the tumor suppressor gene NF2." (PMID 40385896, 2025). "This mouse model of schwannoma development impressively reproduces the genetic profile of schwannomatosis-associated schwannomas with concomitant loss of both Smarcb1 and Nf2." (PMID 40794298, 2025). "Schwannomas are caused by mutations in the loss-of-function NF2 tumor suppressor gene or a loss of chromosome 22, where the NF2 gene is located." (PMID 40940747, 2025). "Building on these results, we further investigated the impact of sEV’s HSP90 on the proliferation of NF2-associated schwannoma cells." (PMID 41149489, 2025). "To achieve this, we focused on NF2-related pathway genes and assessed their expression levels in NF2-associated schwannoma cells with either HSP90 knocked down or overexpressed." (PMID 41149489, 2025). "Further Western blot analysis of HSP90 in NF2-associated schwannoma tissues provided further confirmation that HSP90 was significantly highly expressed." (PMID 41149489, 2025). "Sporadic NF2 mutations have been implicated in several cancers, including sporadic meningioma, ependymoma, and schwannoma, mesothelioma, breast cancer, hepatocellular carcinoma, prostate cancer, glioblastoma, thyroid cancer, melanoma, and renal cell carcinoma." (PMID 39796693, 2024). "In this study, we explored the possibility of treating NF2-deficient schwannomas with Group I PAK inhibitors, TEAD inhibitors, or combinations of the two." (PMID 39083549, 2024). "Next, we analyzed the HEI-193 human schwannoma line, which has a point mutation that causes a splicing defect in the NF2 transcript, and thereby a partial NF2 loss-of-function." (PMID 38879607, 2024). "We showed that genetic ablation of YAP blocks cell growth in HEI-193 cells and that TEAD inhibitors are effective at reducing Hippo target gene expression and in reducing cell number of NF2-deficient schwannoma cells at 72 hours post treatment." (PMID 39083549, 2024). "An NF2 gene panel of over 200 schwannomas, including NF2-schwannomas, sporadic schwannomas, and schwannomatosis-related schwannomas, found that 79% of these tumors had a second mutational event that causes sporadic tumor formation." (PMID 39796693, 2024). "Schwannomas are associated with loss of NF2, a tumor suppressor that modulates numerous downstream effectors including PAK signaling, the Hippo pathway, apoptosis, contact inhibition, and the proteasome." (PMID 38216572, 2024). "In summary, we demonstrated that in NF2-deficient schwannoma, TEAD inhibition and Group I PAK inhibition are successful in preventing cell growth." (PMID 39083549, 2024). "Mutations in the NF2 gene, which encodes the protein merlin, are often associated with the development of schwannomas." (PMID 39233934, 2024). "Distinct features of neurofibromatosis 2 mainly include the development of tumors that arise from Schwann cells, like vestibular NF2-related schwannomas that can be associated with tinnitus, hearing loss, and balance dysfunction." (PMID 38541874, 2024). "Studies have shown evidence for additional somatic mutations in NF2 in schwannomas characterized by germline mutations in LZTR1 or SMARCB1, further supporting evidence for the four-hit/three-step model of schwannomagenesis." (PMID 39796693, 2024).
schwannoma (continued). "NF2 pathogenic variants have been identified in spontaneously occurring schwannomas and meningiomas, as well as many types of cancer including mesothelioma, glioma multiforme, breast, colorectal, skin, hepatic and prostate." (PMID 38336988, 2024). "In this study, we demonstrate the efficacy of Group I PAK inhibition and TEAD-YAP binding inhibition in NF2-deficient schwannoma cells." (PMID 39083549, 2024). "Schwannoma, an intracranially acoustic nerve schwannoma, is linked to neurofibromatosis 2 and loss of NF2 expression." (PMID 36950216, 2023). "Schwannomas that arise in the general population also contain NF2 mutations and represent 8% of all intracranial tumors." (PMID 36809290, 2023). "More studies are needed to clarify the role of non-NF2 gene mutations in the pathogenesis of schwannomas." (PMID 37813009, 2023). "Bilateral schwannomas are typically associated with the condition NF2 and this case is presumed to have either mosaicism for NF2 or sporadic development of bilateral tumours." (PMID 37904024, 2023). "Virtually all schwannomas result from inactivation of the NF2 tumor suppressor gene with few, if any, cooperating mutations." (PMID 36944680, 2023). "Schwannomas are mainly caused by NF2 tumour suppressor inactivation, but they display intratumoural heterogeneity." (PMID 36944680, 2023). "In patients with NF2-associated schwannoma (who typically have bilateral VS), down-regulation of Rac1 activity inhibited proliferation and induced apoptosis in schwannoma." (PMID 37048724, 2023). "Their model was able to preserve patient NF2 mutations, gene expression patterns mimicking patient tumor profiles, and many critical signaling pathways that are often dysregulated in human schwannomas." (PMID 37217995, 2023). "Overall, establishing a reproducible experimental model of NF2-associated schwannoma has become a primary objective for the development of innovative and successful treatment methods, and there is a critical demand to fill this gap with further research." (PMID 37217995, 2023). "Schwannomas arise from Schwann cells in peripheral nerves and have the highest genetic association with NF2, with vestibular schwannomas being a hallmark of the disease." (PMID 36479403, 2022). "By applying a combination of an NF2 mutation type/location, and age of symptom onset, we classified different degrees of functional preservation and progression, schwannoma growth rate and total interventions per year per patient." (PMID 35681071, 2022). "NF2 predisposes individuals to schwannoma development, with bilateral vestibular schwannomas (VS) being a characteristic feature." (PMID 35332608, 2022). "Recently, a clinical trial using a VEGFR1/2 peptide vaccine was also conducted in patients with progressive NF2-associated schwannomas, which was the first immunotherapeutic approach for NF2 patients." (PMID 35628268, 2022). "Human NF2-associated schwannoma cell line BNI-VS-50 established from patient-derived xenograft was used to evaluate the antitumor potential of QDSJ decoction." (PMID 36059985, 2022). "Among them, the loss of the function of merlin, a tumor suppressor protein encoded by NF2 gene, is an important step in the pathogenesis of schwannoma, and the biallelic mutation of NF2 is also found in some sporadic VSs." (PMID 36304995, 2022). "To test the antitumor efficacy of QDSJ decoction, we employed our patient-derived NF2-associated schwannoma cell line and xenograft models." (PMID 36059985, 2022). "The clinical treatment of NF2-associated schwannoma is still a challenge due to the high risk of morbidity." (PMID 36059985, 2022). "In the case of sporadic schwannomas, these events occur independently in both alleles of the NF2 gene, leading to somatic biallelic inactivation." (PMID 36672540, 2022).
schwannoma (continued). "Many of the somatic samples were obtained from schwannoma and meningioma tumors, however, 15 of the variants were identified exclusively in non‐NF2 related tumor types, such as liver, breast and lung cancers." (PMID 35332608, 2022). "In SMARCB1 (INI1) mutation-positive schwannomas, there can be additional genetic alterations, including loss of one copy of chromosome 22 and inactivating mutations in the NF2 gene." (PMID 34072574, 2021). "As a single agent, brigatinib inhibited viability of mouse Nf2-/- schwannoma MS02 and human NF2-deficient HS01 Schwann cells." (PMID 34264955, 2021). "Several MEK inhibitors are under investigation for the treatment of NF2-associated schwannomas and these agents have demonstrated some efficacy at reducing growth in mouse models and in vitro studies." (PMID 31161239, 2020). "mTOR signaling has also been experimentally demonstrated to be dysregulated in NF2-associated schwannomas, and clinical trials with mTOR inhibitors such as everolimus and sirolimus have shown efficacy in reducing the growth of tumors in NF2 patients." (PMID 31161239, 2020). "Consistently, the occurrence of both somatic mutations and CNAs in NF2 has been reported to result in schwannoma by previous studies." (PMID 33193598, 2020). "Schwannomas derive from tumorigenic Schwann cells, caused by loss-of-function mutations of the Nf2 tumor suppressor gene." (PMID 32616891, 2020). "Patients typically harbor tumors of the central nervous system (e.g., meningiomas, schwannomas, ependymomas), but schwannomas of the peripheral nervous system occur as well as a NF2-associated peripheral neuropathy." (PMID 32548671, 2020). "Immunohistochemistry in both NF2-associated and sporadic human schwannomas shows evidence of activated MAPK signaling including increased phospho-AKT, phospho-MEK, and phospho-ERK, as well as increased nuclear c-JUN." (PMID 31161239, 2020). "Lastly, although the functions of INI1/SMARCB1 and LZTR1 in schwannomagenesis are still unclear, recent research shows that subsequent biallelic loss of Nf2 is necessary to induce schwannoma formation." (PMID 32960816, 2020). "Despite these advances, no trial-proven medical therapies have been FDA approved to date for NF2-associated schwannomas." (PMID 31161239, 2020). "Immunostaining of a cohort of NF2-associated schwannomas showed VEGF expression in 100% of vestibular schwannomas and VEGFR-2 in 32% of tumor vessels." (PMID 31161239, 2020). "Increased membrane levels, phosphorylation and activity of ErbB2 and ErbB3 are observed in peripheral nerves of Nf2-deficient mice and patients with schwannomas, contributing to tumor growth." (PMID 32299434, 2020). "Specifically, mutation of the NF2 gene is the most characteristic genetic risk factor for schwannoma." (PMID 33193598, 2020). "Like other schwannomas, NF2-associated vestibular schwannomas frequently exhibit prominent perivascular hyalinization and/or degenerative atypia (“ancient change”) as well as strong and diffuse S100 staining by immunohistochemistry." (PMID 31161239, 2020). "In Nf2-deficient schwannomas, the Hippo transcription factor YAP induces the transcription of prostaglandin and amphiregulin, which activate EGFR." (PMID 32299434, 2020). "Schwannomas are Schwann cell-derived nerve sheath tumors that appear sporadically and in association with genetic tumor syndromes such as NF2." (PMID 32616891, 2020). "In accordance with the somatic mutations and InDels, NF2, harbored in the cytoband 22q11, was also identified to be frequently deleted in the samples of schwannoma." (PMID 33193598, 2020). "Exclusion criteria for schwannomatosis include at least one of the following: germline pathologic NF2 mutation; diagnostic criteria for NF2 fulfilled; first degree relative with NF2; schwannomas occurring in a region of previous radiation therapy." (PMID 31598201, 2019).
schwannoma (continued). "The NF2 gene (on chromosome 22q) and the merlin protein that the gene encodes are implicated in the genesis of about 60% of sporadic schwannomas." (PMID 30710876, 2019). "The mammalian Hippo pathway has been a source of great interest in the development of NF2-deficient schwannomas." (PMID 29416648, 2018). "The neurofibromatosis type 2 (NF2) gene encodes merlin, a tumor suppressor protein frequently inactivated in schwannoma, meningioma, and malignant mesothelioma (MM)." (PMID 29587439, 2018). "Mutations in the tumor suppressor gene NF2 lead to Neurofibromatosis type 2 (NF2), a tumor predisposition syndrome characterized by the development of schwannomas, including bilateral vestibular schwannomas with complete penetrance." (PMID 29416648, 2018). "Merlin’s link to the control of cell proliferation is evidenced by the fact that human schwannomas, meningiomas and mesotheliomas usually exhibit a loss of both Nf2 alleles." (PMID 29715273, 2018). "NF2-associated and sporadically occurring schwannomas are known to be caused by biallelic inactivation of the NF2 gene." (PMID 27921248, 2017). "This is concluded from the observation of frequent somatic, tumour-specific NF2 mutations, and the loss of the second NF2 allele in schwannomas from patients with germline SMARCB1 mutations." (PMID 27921248, 2017). "Following the loss of NF2 expression, schwannoma cultures demonstrated increased proliferation rates." (PMID 28710469, 2017). "NF2 is also associated with schwannomas of other cranial, spinal, and cutaneous nerves; meningiomas and, less frequently, ependymomas." (PMID 28710469, 2017). "By contrast, mitotic recombination accounts for 19% of the LOH events in NF2-associated schwannomas (14 of 72 schwannomas analysed) and 23% (5/22) of schwannomas from schwannomatosis patients without germline SMARCB1 mutations." (PMID 27921248, 2017). "In the genetic study, the mutated sporadic schwannomas however exhibited different NF2 gene statuses, i.e., the ‘one hit’ and the ‘two-hits’." (PMID 28710469, 2017). "We also defined an early spatio-temporal window during which Smarcb1 loss results in malignant tumor formation and showed that biallelic Nf2 loss is necessary and Smarcb1 loss is dispensable for schwannoma formation." (PMID 28824165, 2017). "Nevertheless, LOH causing copy-number loss in 22q represents the most frequent second-hit mutation observed in ~50% of all NF2-associated schwannomas and 69% of sporadic schwannomas." (PMID 27921248, 2017). "Patients with NF2 are at increased risk of developing schwannomas, meningiomas, and gliomas, such as astrocytomas." (PMID 26709712, 2016). "Deletion and loss-of-function mutations of NF2 are associated with development and/or invasiveness of several cancers such as schwannomas, meningiomas, ependymomas, mesothelioma, endometrial cancer, ovarian cancer, glioblastoma, and breast cancer." (PMID 27213454, 2016). "In virtually all sporadic schwannomas, as well as in NF2 disease, schwannoma development is genetically caused by mutations in the Nf2 gene, which encodes for the merlin tumor suppressor protein." (PMID 27236462, 2016). "Using the macrophage mannose receptor MMR/CD206 as an additional non-lysosomal marker, M2-type macrophages were observed in human tissue of both sporadic and NF2-associated schwannomas." (PMID 27236462, 2016). "A hallmark of NF2 disease is the development of Schwann cell tumors (schwannomas) at the vestibulocochlear nerve, referred to as vestibular schwannomas." (PMID 27467574, 2016). "The finding that virtually all sporadic and NF2-associated human schwannomas tested in this study show macrophage presence, further supports the concept that schwannoma formation is promoted by an unresolved inflammatory response." (PMID 27236462, 2016).